OXTR (oxytocin receptor)
Description:
G protein-coupled receptor for oxytocin (OXT), a neuropeptide hormone released by the posterior pituitary gland that plays a key role in social behavior and other biological processes, such as milk ejection. Ligand binding causes a conformation change that triggers signaling via guanine nucleotide-binding proteins (G proteins) and modulates the activity of downstream effectors, such as phospholipase C. OXTR is mainly coupled to G(q) G proteins and mediates production of diacylglycerol (DAG) and inositol 1,4,5-trisphosphate (IP3) second messengers that modulate the activity of phosphatidylinositol 3-kinase and promote the release of Ca(2+) ions from intracellular stores, respectively. In presence of high levels of oxytocin, also coupled to G(i) G proteins, mediating inhibition of adenylate cyclase activity. Central release of oxytocin plays essential roles in social behavior, such as maternal care, social cognition and affiliative behaviors, triggering signaling that modulates neural circuits by altering ion channel activity, changing intrinsic neuronal properties and modifying synaptic transmission (both excitatory and inhibitory). Peripheral release of oxytocin (secretion into the bloodstream) promotes various processes, such as parturition, lactation or osteoblast differentiation. OXTR-mediated signaling promotes milk ejection by triggering and strengthening contraction of the smooth muscle of mammary gland (By similarity).
Synonyms: OT-R; OTR
Tractability: Small molecule: a drug acting on it is in phase 2 or 3 trials; a structure with a bound ligand is known; a high-quality ligand is known; it belongs to a druggable protein family. Antibody: its Gene Ontology location is reachable by antibodies, with high confidence; UniProt places it where antibodies can reach, with medium confidence; UniProt predicts a signal peptide or a membrane-spanning region. PROTAC: ubiquitination databases record sites on it; a small molecule that binds it is known. Other modalities: an approved drug acts on it.
Target class: Family A G protein-coupled receptor; Vasopressin and oxytocin receptor; Short peptide receptor (family A GPCR); Membrane receptor; Peptide receptor (family A GPCR)
Chemical probes: L-371,257 (high quality), PF-3274167 (high quality), SHR1653 (high quality)
Gene: Protein-coding gene on chromosome 3 (8,750,381 to 8,769,628, reverse strand). Ensembl gene ENSG00000180914.
Subcellular location: Cell membrane
Pathways (Reactome):
Signal Transduction: G alpha (q) signalling events; Vasopressin-like receptors
Gene Ontology:
Molecular function: oxytocin receptor activity; vasopressin receptor activity; G protein-coupled receptor activity
Biological process: adenylate cyclase-inhibiting G protein-coupled receptor signaling pathway; fetal process involved in parturition; phospholipase C-activating G protein-coupled receptor signaling pathway; positive regulation of uterine smooth muscle contraction; social behavior; cell surface receptor signaling pathway; cellular response to hormone stimulus; female pregnancy; G protein-coupled receptor signaling pathway; lactation; maternal behavior; maternal process involved in parturition; milk ejection reflex; muscle contraction; positive regulation of cold-induced thermogenesis; positive regulation of osteoblast differentiation; positive regulation of vasoconstriction; regulation of synaptic plasticity; regulation of systemic arterial blood pressure by vasopressin; female mating behavior
Cellular component: plasma membrane; membrane
Genetic constraint (gnomAD): Loss-of-function variants: 21 observed, 23.67 expected, observed/expected ratio (o/e) 0.89, 90% interval 0.63 to 1.28. The upper end of that interval is the gene's LOEUF score, 1.28, which puts it in group 5 of 6, group 1 being the genes least tolerant of losing a copy. Missense variants: 500 observed, 522.81 expected, observed/expected ratio (o/e) 0.96, 90% interval 0.89 to 1.03. Synonymous variants: 278 observed, 242.55 expected, observed/expected ratio (o/e) 1.15, 90% interval 1.04 to 1.27.
Homologues: Orthologues: chimpanzee OXTR (99% identical), macaque OXTR (97% identical), mouse Oxtr (92% identical), rat Oxtr (92% identical), dog OXTR (91% identical), guinea pig OXTR (89% identical), pig OXTR (87% identical), tropical clawed frog oxtr (68% identical), zebrafish oxtrb (63% identical), zebrafish oxtra (63% identical), Drosophila melanogaster CCAP-R (30% identical). Paralogues in human: AVPR1B (50% identical), AVPR1A (47% identical), AVPR2 (37% identical), CCKBR (24% identical), CCKAR (23% identical), GPR150 (23% identical), HCRTR2 (22% identical), GNRHR (21% identical), HCRTR1 (20% identical), FFAR4 (20% identical), GALR3 (20% identical), NPFFR2 (19% identical), and 4 more.
Diseases named in the same sentence as OXTR in open-access papers:
OXTR is named in the same sentence as 186 diseases in open-access papers, as found by Europe PMC text mining. Sharing a sentence is not in itself a finding about the gene and the disease. The quoted sentences say what the papers report.
Anxiety (105 papers, 2010 to 2026). Intense feelings of nervousness, tension, or panic often arise in response to interpersonal stresses. "Another area of research has found that variation in the oxytocin receptor gene (OXTR) is linked to individual differences in social behaviors, early life stress, depression, and anxiety." (PMID 40076753, 2025). "Similar findings are reported for the OXTR polymorphism rs2254298, which associates with depression and anxiety in adults and, in the face of early adversity, associates with anxiety and depression in adolescent girls." (PMID 40076753, 2025). "A single-nucleotide polymorphism (rs2254298, A>G) in the oxytocin receptor gene (OXTR) has been extensively associated with altered social stress reactivity and susceptibility to anxiety and depression." (PMID 41356682, 2025). "OXTR variants were found to be nominally associated with the severity of overall symptoms, hostility symptoms and anxiety symptoms." (PMID 38184684, 2024). "Recent studies showed that the genetic variant of OXTR rs2254298 influences the neurobiology of attention-deficit hyperactivity disorder and anxiety, leading to more significant functional, social, and emotional impairment." (PMID 37520225, 2023). "The OXT/OXTR signaling is implicated in a variety of normal behaviors, including social interaction, anxiety-related behavior, depression, maternal behavior, aggression, mating, attachment, and sexual behavior." (PMID 37153633, 2023). "From the perspective of gene–environment interactions, this interaction fits the differential susceptibility model; OXTR rs2254298 GG homozygote carriers are susceptible to the environment and are likely to experience anxiety symptoms of alcohol withdrawal." (PMID 37520225, 2023). "In humans, the genetic variability in the OXTR rs2254298 variant determines the volume of the amygdala, a brain structure involved in the control of fear and anxiety." (PMID 38002996, 2023). "Genotype for 5-HTTLPR, STin and AVPR1a and haplotype for HTR2A and OXTR were significantly associated with the duration of behaviours including fear and anxiety." (PMID 37531334, 2023). "Genotype for 5-HTTLPR, STin and AVPR1a, and haplotype for HTR2A, DRD4 and OXTR were significantly associated with the duration of behaviours including fear and anxiety." (PMID 37531334, 2023). "The OXTR+ mPFC interneurons have obvious sexual dimorphism in social behavior; activation of these neurons causes anxiety in males but promotes social behavior in females." (PMID 37445607, 2023). "Prenatal OXTR deficiency potentiates maternal diabetes-mediated anxiety-like behavior but has little effect on ALB; additionally, postnatal OXTR expression partly, while postnatal ERβ expression completely, reversed maternal diabetes-mediated social deficits." (PMID 33633538, 2021). "In vivo mouse study showed that prenatal OXTR deficiency potentiates maternal diabetes-mediated anxiety-like behavior, while it has little effect on ALB." (PMID 33633538, 2021). "Our results indicate that prenatal OXTR deficiency potentiates maternal diabetes-mediated anxiety-like behavior, while it has little effect on ALB in male offspring." (PMID 33633538, 2021). "In female mandarin voles, chronic social defeat stress has been reported to induce anxiety‐related and depression‐related behaviour associated with a reduction of oxytocin fibres and oxytocin receptor mRNA in the nucleus accumbens." (PMID 34713517, 2021). "We found that prenatal OXTR deficiency induces many social deficits in offspring, it mimics the effects of maternal diabetes-induced anxiety-like behavior and ultrasonic vocalization, while has little effect on ALB." (PMID 33633538, 2021). "Cnr1-/- dams show deficits in maternal care (pup retrieval), which is likely caused by their increased anxiety state and correlated with reduced oxytocin receptor and BDNF expression in the hippocampus." (PMID 32997200, 2021).
Anxiety (continued). "It was reported that the GG genotype of OXTR rs2254298 was positively linked to depression and anxiety in the Caucasian sample, which was similar to our finding: GG individuals had lower SWB." (PMID 35222513, 2021). "Regarding OXTR methylation and behavior, lower levels of OXTR methylation and higher plasma oxytocin levels are associated with less socioemotional anxiety in young adults." (PMID 34576011, 2021). "The potential role of OXTR gene polymorphism in depression and anxiety has been suggested by several studies, with little attention on positive affect." (PMID 35222513, 2021). "This study shows that SNP rs41423247 in the NR3C1 gene and SNP rs53576 in the OXTR gene are associated with self-assessed anxiety in healthy individuals in a gender-specific manner." (PMID 32957930, 2020). "OXTR encodes the G protein related to the oxytocin receptor, which regulates anxiety, bonding and maternal behaviour." (PMID 30202991, 2018). "All behavioral aspects measured in the SST (Attachment, Anxiety, and Acceptance) showed significant association with all three dog OXTR SNPs investigated in this study (as a main or an interaction effect)." (PMID 29674985, 2018). "This seems to result from the facts that sex of the dogs influenced the associations of two canine OXTR SNPs, namely the effects of −213AG and −74CG on dogs' Anxiety." (PMID 29674985, 2018). "The effects of dog OXTR polymorphisms and dog characteristics on Attachment, Anxiety, and Acceptance composite scores as measured in the Strange Situation Test." (PMID 29674985, 2018). "Summary of the effects of dog and owner OXTR polymorphisms on dogs' Attachment, Anxiety, and Acceptance composite scores as measured in the Strange Situation Test." (PMID 29674985, 2018). "Depression and anxiety in turn have been associated with higher levels of OXTR methylation, and these were moderated by the OXTR SNP rs53576." (PMID 28353027, 2017). "There are indications that OXTR single nucleotide polymorphisms (SNPs) interact with early life stressors in predicting levels of depression and anxiety." (PMID 28353027, 2017). "Most evidence so far for involvement of the OXTR gene in both anxiety and depression comes from candidate gene studies looking at associations between OXTR SNPs and (endo-)phenotypes of anxiety and depression." (PMID 28353027, 2017). "The null findings regarding associations between OXTR SNPs and anxiety are also in line with a recent GWA study." (PMID 28353027, 2017). "Very similar findings are reported for the OXTR polymorphism rs2254298, which associates with depression and anxiety in adults and, in the face of early adversity, associates with anxiety and depression in adolescent girls." (PMID 23637833, 2013). "Findings lend support to a modulatory effect of common OXTR variants on Harm Avoidance in healthy caucasian women and invite resequencing of the gene in anxiety phenotypes to identify more explanatory functional variation." (PMID 22846218, 2012). "Other behavior-related genes are gamma-aminobutyric acid type A receptor subunit alpha 6 (GABRA6), which plays a role in inhibitory neurotransmission and anxiety regulation, and oxytocin receptor (OXTR), which has been linked to social bonding and stress coping mechanisms." (PMID 40002435, 2025). "In summary, we have identified that OXTR polymorphisms were nominally associated with the severity of overall symptoms, hostility symptoms and anxiety symptoms of schizophrenia and with the improvement in negative symptoms apathy/avolition and hostility symptoms." (PMID 38184684, 2024). "Our results suggested that OXTR polymorphisms might play a role in the genetic foundation making schizophrenia patients differ in the severity of anxiety symptoms." (PMID 38184684, 2024).
Anxiety (continued). "We found that OXTR polymorphisms were nominally associated with the severity of overall symptoms (rs237899, β = 1.669, p = 0.019), hostility symptoms (rs237899, β = 0.427, p = 0.044) and anxiety symptoms (rs13316193, β = −0.197, p = 0.038)." (PMID 38184684, 2024). "OXT is known to have stress-protective and anxiolytic effects and low levels of OXTR expression in brain regions responsible for emotional and social behaviors are hypothesized to be associated with high anxiety levels." (PMID 38645599, 2024). "Therefore, this study focused on the interactive effects of OXTR rs2254298 and alcohol withdrawal on depressive or anxiety symptoms, exploring protective genotypes/susceptibility genotypes." (PMID 37520225, 2023). "It is easy to infer that the dysfunction of OXTR may be implicated in anxiety-like or depression-like behaviors." (PMID 37153633, 2023). "Finally, re-parameterized regression analysis demonstrated that this gene–environment interaction of OXTR rs2254298 and alcohol dependence on anxiety fits the weak differential susceptibility model (R2 = 0.17, F = 13.46, p < 0.001)." (PMID 37520225, 2023). "Furthermore, our in vivo mouse study showed that maternal diabetes induces OXTR suppression; prenatal OXTR deficiency mimics and potentiates maternal diabetes-mediated anxiety-like behaviors, while there is less of an effect on autism-like behaviors." (PMID 33633538, 2021). "Interestingly, in all of these studies the OXTR gene polymorphisms interacted with stressful life experiences in predicting levels of anxiety or depression." (PMID 28353027, 2017). "OXTR gene variations have often been linked to autism spectrum disorders, but the OXTR gene may be involved in the development and/ or maintenance of anxiety and depressive disorders as well." (PMID 28353027, 2017). "Furthermore, there have been studies examining associations between OXTR gene polymorphisms and levels of anxiety and depression in community samples." (PMID 28353027, 2017). "Furthermore, we identified that the extended OXTR cumulative genetic risk score itself was significantly associated with maternal separation anxiety from the infant; however this association was driven specifically by rs968389." (PMID 27872764, 2016). "Interaction of the OXTR genotypes with positive behaviors such as empathy and trust or, conversely, with adverse environments such as exposure to abuse shapes either lower or greater risk for depression and anxiety, respectively." (PMID 27872764, 2016). "We tested “evocative” gene-environment interaction using ASA and found a significant G × E association between the OXTR cumulative genetic risk score and adult separation anxiety assignment on observed maternal sensitivity during free play of the SFP (p = 0.007∗∗, R2 = 14%)." (PMID 27872764, 2016). "Performing a multiallelic analysis across OXTR by calculating a cumulative genetic risk score revealed a significant gene-by-environment (G × E) interaction, with OXTR genetic risk score interacting with adult separation anxiety to modulate levels of maternal sensitivity." (PMID 27872764, 2016). "Moreover, the extended cumulative OXTR genetic risk score itself was found to be significantly associated with maternal separation anxiety as it specifically relates to the infant." (PMID 27872764, 2016). "In addition, polymorphisms in the OXTR can result in decreased receptor expression, symptoms of depression and anxiety, and sensitivity to stressors." (PMID 24143878, 2013). "Oxytocin receptor polymorphisms have been associated with depression and anxiety, and oxytocinergic activity has been shown to be dysregulated in women with both unipolar and bipolar depression, and it has been suggested as a potential therapeutic target for mental disorders." (PMID 24143878, 2013). "Thus, OXTR polymorphisms may influence the susceptibility to anxiety in patients with different genotypes through methylation of OXTR." (PMID 38184684, 2024).